IL10 (interleukin 10)
Diseases named in the same sentence as IL10 in open-access papers (continued):
Sharing a sentence is not in itself a finding about the gene and the disease.
lymphopenia (continued). "Both lymphopenia and T cell exhaustion were directly correlated with the increase in the levels of IL-6, IL-10, and TNF alpha and with disease severity." (PMID 33072103, 2020). "From the little we know in the inflammatory response triggered by SARS-CoV-2, during this infection lymphopenia is observed, with loss of CD4 + and CD8 + T cells, hyperproduction of IL6, IL10, IL2R, TNFa and CCL2." (PMID 32883368, 2020). "Older age, lymphopenia, leukocytosis, neutrophilia, thrombocytopenia, hyperglycemia and elevated d-dimer, LDH, hsCRP, IL-8, and IL-10 were also associated with death." (PMID 33382747, 2020). "Such increase was negatively correlated with CD4+ T cell lymphopenia and positively with increased IL-10 production by monocytes." (PMID 33613540, 2020). "Parallels seen in late-stage disease mice include: high viral loads (RNAemia), elevated AST and ALT, elevated neutrophils, lymphopenia, and increases in IL-10, IL-6, IFN-γ, CCL2, CCL5, and TNF-α." (PMID 31790513, 2019). "Exposure to ionizing radiation at specific dose and radiation qualities can lead to lymphopenia, and the genes for IL7, along with IL10 and Flt3 ligand, encode positive regulators of the lymphoid lineage after TBI." (PMID 30978983, 2019). "The high production of the cytokines IL-10 and IL-5 with CD4 lymphopenia is likely to be a cause of the aggressive disease and the pulmonary spread." (PMID 27711109, 2016). "Compared with controls, acute UCM was associated with mild lymphopenia, splenomegaly, and high levels of IFN-γ, tumor necrosis factor-α, and IL-10, which normalized in convalescence." (PMID 26335932, 2015). "Some studies suggest a potential link between lymphopenia and elevated levels of IL‐10, TNF or IL‐6, which may act directly on lymphocytes or indirectly via other cell lineages (e.g. neutrophils and DCs)." (PMID 41163794, 2025). "FMDV induces immunosuppression through IL-10-mediated lymphopenia and T cell dysfunction." (PMID 41156600, 2025). "Similarly, studies in mice have suggested that FMDV-induced lymphopenia can be prevented by blocking IL-10/IL10R signaling, improving survival post-FMDV infection in this species." (PMID 40524230, 2025). "Additionally, the relevance of IL-10 and potential lymphopenia during FMDV infection in cattle is contested and should be investigated further, particularly with regard to its possible impact on the carrier/non-carrier divergence." (PMID 40524230, 2025). "Moreover, it has been reported that tumor secretion of TNF-α and IL-10 leads to lymphopenia and lymphocyte dysfunction." (PMID 37190296, 2023). "It was noted that IL-10 mediated lymphopenia in mice infected with FMDV." (PMID 37047294, 2023). "In addition, IL-10 mediated lymphopenia in C57BL/6 mice infected with FMDV, and blocking IL-10/IL-10R signaling in vivo or knocking out IL-10 inhibited the trafficking of B cells in peripheral blood to the heart." (PMID 37047294, 2023). "After SARS-CoV-2 recovery, IL-10 levels reduced, probably due to lymphopenia restoration." (PMID 37240647, 2023). "Lymphopenia is mediated by the overmentioned inflammatory cytokine milieu (especially rich in IL-6, IL-10, and TNF-α), via lymphocyte sequestration into lymphoid tissue and endothelia by IFN-I and TNF-α or by extensive cell death triggered by IL-6 and Fas-FasLigand signaling." (PMID 33996683, 2021). "Thus, the elevated IL-10 in the serum is able to induce T-cell apoptosis in the peripheral blood, which contributes to lymphopenia during FMDV infection." (PMID 34960627, 2021). "Notably, elevated IL-10 not only coincided with the occurrence of lymphopenia but, also, with elevated levels of CXCL13." (PMID 34960627, 2021). "Interestingly, IL-10 but not TNF-α in the serum from infected mice was upregulated following FMDV infection, and the elevated levels of IL-10 coincided with the occurrence of lymphopenia in this study." (PMID 34960627, 2021).
lymphopenia (continued). "IL-10-/- or blocking IL-10/IL-10R signaling in vivo is able to prevent lymphopenia via downregulating apoptosis, trafficking, and the expression of coinhibitory molecules of lymphocytes from FMDV-infected mice, which contribute to enhance the survival of mice infected with FMDV." (PMID 34960627, 2021). "Knocking out IL-10 (IL-10-/-) mice or blocking IL-10/IL-10R signaling in vivo was able to prevent lymphopenia via downregulating apoptosis, trafficking, and the coinhibitory expression of lymphocytes in the peripheral blood, which contribute to enhance the survival of mice infected with FMDV." (PMID 34960627, 2021). "Third, lymphopenia is partially a consequence of increased apoptosis in antigen-specific and nonspecific T cells, which is associated with disease severity and where SARS-CoV-2-specific subsets, such as IL-10 secreting T cells, appear to be more susceptible." (PMID 34021148, 2021). "Current studies suggest that CD4+ T-cell lymphocytopenia coupled with increases in IL-10-producing regulatory subsets specifically within the CNS may be most relevant." (PMID 29456537, 2018). "We hypothesised that the KT ratio would be related to IFN-γ and IL10 concentrations, and inversely related to both T cell lymphopenia and microvascular reactivity, a measure of endothelial NO bioavailability." (PMID 21731667, 2011). "The mechanisms responsible for lymphopenia also involve margination and redistribution of lymphocytes within the lymphatic system, along with accelerated apoptosis through tumor-related cytokines, particularly interleukin-10 (IL-10) and tumor necrosis factor beta." (PMID 40869673, 2025). "Contrary to earlier beliefs, apoptosis is not the cause of this lymphopenia; instead, elevated IL-10 levels during infection may be implicated." (PMID 39340101, 2024). "Furthermore, IL-10 produced by CD9+-regulatory B cells was found to induce T-cell apoptosis, which indicated that IL-10 may be involved in lymphopenia." (PMID 34960627, 2021). "Thus, it is possible that IL-10 overproduction in the patient with fatal HME could be another potential mechanism that account for observed lymphopenia and week Th1 response." (PMID 22607204, 2012). "An immunosuppressive stage modulated by IL-10 during acute FMDV infection of this species has been reported, with elevated IL-10 levels contributing to lymphopenia and potentially dampening antiviral activity." (PMID 40524230, 2025). "Our recent study found that interleukin-10 (IL-10) and CXCL13 were obviously elevated in sera from mice infected with FMDV and were related to lymphopenia and the progression and severity of the disease." (PMID 37047294, 2023). "These patients also showed variation of some of the other haematological parameters tested at admission: increased IL-6, IL-10 and CRP, leucocytosis, neutrophilia, and lymphopenia." (PMID 37215142, 2023). "Blood concentration of sP2X7R was also increased, and significantly positively correlated with lymphopenia, procalcitonin (PCT), IL-10, and alanine transaminase (ALT)." (PMID 37215142, 2023). "The results showed also a highly significant increase in the concentration levels of serum IL-10 (P value = 0.04*)) and serum TLR-4 (P value = 0.006*)) in patients having lymphopenia." (PMID 36864077, 2023). "The results showed significant increases in the levels of serum IL-10 and TLR-4 in patients having lymphopenia compared to patients with normal lymphocytic count." (PMID 36864077, 2023). "Similarities included resolution of lymphopenia and neutrophilia and a rapid decrease in the serum concentrations of CRP, TNF-α, IL-6, IFN-γ, IL-10, TNFR-1, and IP-10 following treatment with Allocetra-OTS." (PMID 37600829, 2023). "For examples, monocyte alterations (CD74, CIITA mRNA), lymphopenia (CD3, IL7R mRNA), increased anti-inflammatory response (IL10, IL1RN mRNA), altered IFN response (OAS2, IFNG mRNA) were observed." (PMID 36389738, 2022).
lymphopenia (continued). "Propranolol was also reported to control acute ischemic stroke patients with lymphopenia through its role in enhancing TNF-α, IL-10, and TNF-α/IL-10." (PMID 35893792, 2022). "T cells reduction in the blood is also a contribution of mechanisms such as inflammatory cytokine milieu, which is why lymphopenia has a correlation with TNF-α, IL-6, and IL-10." (PMID 33716737, 2021). "Fewer platelets, CD3 or CD4 counts, lower complement C3 level, lymphopenia, and elevated APTT, IL-6 or IL-10 also were related to the progression from oneset to death (all P < 0.05)." (PMID 32903644, 2020). "We found that children recruited with acute UCM presented with lymphopenia and splenomegaly and higher than normal levels of IFN-γ, TNF-α, and IL-10, which normalized 1 month into convalescence." (PMID 26335932, 2015). "Potential mechanisms may involve lymphocyte-mediated vascular repair through anti-inflammatory cytokines such as IL-10, while patients with WMH often exhibit immunosenescence, characterized by lymphopenia and elevated C-reactive protein (CRP) levels." (PMID 41425912, 2025). "IL-10 and TLR4 levels were significantly higher in patients having lymphopenia." (PMID 36864077, 2023). "Additionally, it is known that glucocorticoids are able to increase the expression of IL-10 and SLE patients usually present lymphopenia secondary to disease activity or related to the immunosuppressant treatment." (PMID 36428917, 2022). "Similarly, in another study, IL-10 is highly correlated with disease activity, SLEDAI, anti-dsDNA, C3, C4, and lymphopenia." (PMID 31697750, 2019). "In summary, FMDV infection of cattle is characterized by production of IL-10 by DC and monocytes, which may be responsible to immunosuppression in cattle, characterized by down-regulation of MHC class II molecules and lymphopenia." (PMID 27008425, 2016). "Interestingly, the elevated IL-10 in the serum was correlated with the appearance of lymphopenia during FMDV infection but not IL-6, IL-2, IL-17, IL-18, IL-1β, TNF-α, IFN-α/β, TGF-β, and CXCL1." (PMID 34960627, 2021). "Besides, a study showed that severe infection by SARS-CoV-2 could create lymphopenia with decreased CD4+ and CD8+, but interestingly, there is no decrease in lymphocytes B. In summary, there is an increase in cytokines IL6, IL2R, IL10, TNFα, and MCP-2 production and a decrease in IFN-γ production." (PMID 34078305, 2021). "From an immunological point of view, the lymphopenia could depend on the possible dysfunctional activation of dendritic cells already mentioned and the high concentration of cytokines such as TNF-α, IL-6, and IL-10, which act as negative regulators of the proliferation and survival of T lymphocytes." (PMID 33324414, 2020). "The absolute numbers of CD19+CD5+CD1dhigh cells, CD19+CD24+CD38+ cells, and CD19+IL-10+ cells increased but not significantly in SLE patients when compared with healthy controls, which might be attributed to peripheral lymphopenia in SLE patients during flares." (PMID 24551101, 2014).
cervical carcinoma (95 papers, 2010 to 2026). A carcinoma arising from either the exocervical squamous epithelium or the endocervical glandular epithelium. "Given the contradictory results of numerous studies on the role of SNP-592C/A of the IL-10 gene in the pathogenesis of cervical cancer, we conducted a meta-analysis to assess the association between SNP-592C/A in the IL-10 gene and the risk of cervical cancer." (PMID 35919032, 2022). "This would need to be addressed in further studies and would be counter to much literature which supports raised IL-10 as risk factor for cervical cancer." (PMID 36330509, 2022). "Eleven available studies, including 4187 cases and 3311 controls, were included in this study investigating the relationship between the -592C/A polymorphism of IL-10 and cervical cancer risk." (PMID 35919032, 2022). "In the present study, including 4187 cases and 3311 controls, we noted that the −592C/A polymorphism of the IL-10 gene was correlated with the overall risk of cervical cancer for the recessive, dominant, and additive models." (PMID 35919032, 2022). "Several candidate gene studies have reported an association to exist between IL-10 promoter polymorphisms and cervical cancer susceptibility." (PMID 34683414, 2021). "The odds ratios (ORs) and 95% confidence intervals (CIs) were calculated to assess the association between IL-10 polymorphisms and cervical cancer risk." (PMID 29552317, 2018). "A total of thirteen relevant studies, consisting of 2,311 patients and 2,491 controls focused on the association between the IL-10 -1082A > G polymorphism and cervical cancer risk." (PMID 29552317, 2018). "Six studies involving 953 cases and 1,082 controls were included in this meta-analysis to assess the association between the IL-10 -819T > C polymorphism and cervical cancer risk." (PMID 29552317, 2018). "Third, the association between the IL-10 -1082A > G, -819T > C and -592C > A polymorphisms and cervical cancer risk were analyzed separately, and the influence of the haplotype and gene-gene interactions was not analyzed due to an insufficient amount of data." (PMID 29552317, 2018). "In summary, our meta-analysis suggests that the IL-10–1082A > G and -819T > C polymorphisms are associated with cervical cancer susceptibility, but with contradictory effects." (PMID 29552317, 2018). "The aim of this study was to conduct a meta-analysis of published reports to more precisely investigate the relationship between IL-10 polymorphisms and cervical cancer risk." (PMID 29552317, 2018). "To date, two meta-analyses have been conducted, examining previously published studies to elucidate the association between IL-10 polymorphisms and cervical cancer risk." (PMID 29552317, 2018). "Since 2001, a large number of molecular epidemiological case-control studies have been conducted to explore the association between IL-10 polymorphisms and cervical cancer risk, but the results have been inconsistent." (PMID 29552317, 2018). "The researchers found that the IL-10 -592C > A polymorphism was associated with an increased risk of cervical cancer development." (PMID 29552317, 2018). "Associations with both increased and decreased IL-10 levels in cervical cancer have been shown in different studies." (PMID 28280748, 2017). "In fact, two studies found an increase in serum IL-10 associated with various stages of cervical cancer." (PMID 28854209, 2017). "In cervical cancer and CIN, the risk and the progression of cervical cancer have been associated with increased IL-10 serum levels." (PMID 23554684, 2011). "Our results point to a possible mechanism behind the epidemiologic data that correlates higher IL-10 expression with risk of cervical cancer development in HPV infected women." (PMID 20525400, 2010). "Moreover, TNF-308 AA and IL-10-592 CA/AA polymorphisms are linked to an increased risk of cervical cancer." (PMID 37704909, 2023).
cervical carcinoma (continued). "The present study shows certain limitations as follows: the limited number of case and control studies carried out on the association of SNP-592C/A in the IL-10 gene with the risk of cervical cancer, particularly in the Caucasian and African populations (almost absent), and the sample size." (PMID 35919032, 2022). "Although genetic variables have been linked to carcinogenesis, the mechanism by which the IL-10 gene polymorphism causes cervical cancer is unknown." (PMID 35919032, 2022). "Regarding ethnicity, a significant association of the -592C/A polymorphism of the IL-10 gene was linked to an elevated risk of cervical cancer for all genetic models (recessive, dominant, and additive) in the Asian populations and for the recessive and additive models in Caucasians with P < 0.05." (PMID 35919032, 2022). "However, mutations in genes involved in cytokine synthesis, such as interleukin 10 (IL-10), appear to be strong predictors of cervical cancer risk." (PMID 35919032, 2022). "The overall analysis showed an increased susceptibility to cervical cancer with the -592C/A polymorphism of the IL-10 gene for the recessive model (OR = 1.30, 95% CI = 1.14–1.49), dominant model (OR = 1.36, 95% CI = 1.09–1.70), and additive model (OR = 1.25, 95% CI = 1.09–1.44)." (PMID 35919032, 2022). "Thus, women harboring the higher IL-10 production variant have an increased risk of cervical cancer and premalignant lesions, which has been verified across several populations." (PMID 34683414, 2021). "Low IL-10 levels are associated with increased risk for cervical cancer." (PMID 31284453, 2019). "Conversely, low IL-10 levels are associated with a higher risk for cervical cancer." (PMID 31284453, 2019). "The limited number of studies and sample size for each polymorphic locus may reduce the reliability of the results and affect the assessment of associations between these IL-10 polymorphisms and cervical cancer susceptibility." (PMID 29552317, 2018). "Previous studies have suggested that interleukin-10 (IL-10) polymorphisms may be associated with an increased risk of developing cervical cancer." (PMID 29552317, 2018). "Moreover, the IL-10 -819 T > C polymorphism exhibited a significant, protective effect against cervical cancer." (PMID 29552317, 2018). "Therefore, we conducted the present meta-analysis to provide a more precise and comprehensive assessment of the relationship between IL-10 polymorphisms and cervical cancer susceptibility." (PMID 29552317, 2018). "For the IL-10 -592C > A polymorphism, ten studies consisting of 3,149 cases and 2,237 controls were pooled in the meta-analysis to assess whether this IL-10 -592C > A polymorphism was associated with cervical cancer risk." (PMID 29552317, 2018). "In contrast, the IL-10–819T > C polymorphism may have a protective effect against cervical cancer development, especially in Asian populations." (PMID 29552317, 2018). "Our results suggest that the IL-10–1082A > G polymorphism may be associated with an increased risk of cervical cancer development." (PMID 29552317, 2018). "In summary, our meta-analysis suggests that IL-10 polymorphisms may play a variety of roles in regard to cervical cancer risk, especially in Asians." (PMID 29552317, 2018). "However, the same meta-analysis did find a significant association for another IL10 promotor SNP (c.-592C>A), with occurrence of the minor allele associated with increased cervical cancer risk, especially among Asian patients." (PMID 28280748, 2017). "Also, women who are genetically programmed to produce high or moderate levels of IL-10 are more likely to develop cervical cancer, compared to individuals genetically predisposed to present low IL-10 production." (PMID 25625305, 2015).